IL10 (interleukin 10)
Diseases named in the same sentence as IL10 in open-access papers (continued):
Sharing a sentence is not in itself a finding about the gene and the disease.
infection (continued). "Ferritin, an ARP, is increased in many inflammatory states, and it may serve as a biomarker for CRS, HLH in hematologic disorders, but when used as a predictor of infection, ferritin is affected by a variety of factors including IL-6, IL-10, IL-18, and IFNγ." (PMID 39559703, 2024). "Post-infection, dietary Glut and 1% omega-3 increased intestinal interleukin-10 (IL) and secretory immunoglobulin-A and serum lysozyme, while decreased the elevated inflammatory mediators comprising interleukin IL-6, tumor necrosis factor-alpha, nitric oxide (NO) and inducible NO synthase." (PMID 38961536, 2024). "This was accompanied by changes in cytokine profiles and parasite loads which were dependent on the cell type (CD4+ T, CD8+ T, NK, NKT and γδ T cells), the organ (SI, PP, MLN, SPL and liver), the time-point (day 5 and 10 post-infection) and the cytokine (IFNγ, IL-4, IL-10 and IL-13) studied." (PMID 38950025, 2024). "In addition, both IFN-γ and IL-10 were significantly elevated in mice co-infected with both Em and Bb, relative to Bb infection alone." (PMID 39229265, 2024). "In addition, infection increased the concentration of IL-10 in intact females, generating a dimorphic pattern in which females exhibited a higher concentration of IL-10 than males." (PMID 37628731, 2023). "During the chronic longstanding infection, a change from inflammatory Th2 phenotype to modified Th2 phenotype is characterized by increasing secretion of IL-10 and TGF-β by regulatory T cells (Tregs) and switching of inflammatory IgE to non-inflammatory IgG4 by regulatory B cells (Bregs)." (PMID 37020538, 2023). "High levels of IL-10 could be stimulated by a high intensity of infection to prevent the development of an excess pathology mediated by Th2 in addition to the Th1-mediated pathology." (PMID 37243099, 2023). "IL-10 protects the host from infection-induced excessive inflammation and tissue injury." (PMID 36719648, 2023). "Additionally, the levels of anti-inflammatory cytokines IL-4 and IL-10 tended to increase at all time points, with significant increases in IL-4 at the 15 and 20 weeks of infection (P < 0.05)." (PMID 38076459, 2023). "Interleukin-10 (IL-10) and IL-10-expressing macrophages were significantly increased in the uterine tissues of WT mice during infection with HylB-proficient GBS compared with those of TLR2/4-deficient mice, and this likely promotes immune suppression and GBS dissemination." (PMID 37747229, 2023). "Infection of macrophages in vitro revealed that pyruvate dehydrogenase was required to prevent phagolysosomal acidification, which altered expression of the immunosuppressive cytokine IL-10." (PMID 37384800, 2023). "The two important features of this process are that MMTV requires commensal gut microbes for productive infection, and that production of IL-10 limits antiviral responses by preventing the formation of neutralizing antibodies (and possibly cellular immunity as well)." (PMID 36869359, 2023). "Interestingly, numerous pathogens, including bacteria but also parasitic pathogens seem to be able to induce IL-10 during infection, thus pivoting the host-pathogen interaction in their favor." (PMID 37637102, 2023). "Both ɣδ and CD4+ T cell infiltrates were significantly increased in the brains of IL-10 KO mice at days 7 and 14 post-infection, respectively, which when combined with the significant reduction in G-MDSCs suggests a transition in the inflammatory milieu in the absence of IL-10." (PMID 37179295, 2023). "In particular, in addition to pro-inflammatory cytokines, we also observed a higher level of anti-inflammatory cytokines (IL-10 and IL-1ra), which may contribute to counteracting and containing the inflammatory response to the infection." (PMID 37242334, 2023). "However, these MDSCs were recruited later during infection with the hypervirulent strain (3 days) and were shown to mediate the resolution of acute pneumonia through the production of IL-10." (PMID 37492184, 2023).
infection (continued). "Since our findings revealed that granulocytes were a major source of IL-10 during S. aureus craniotomy infection with less production by microglia and monocytes, we generated Mrp8CreIL-10 fl/fl and CX3CR1CreIL-10 fl/fl mice to target each population, respectively." (PMID 37179295, 2023). "Interestingly, the ratios of IFN-γ/IL-4 and IFN-γ/IL-10 were elevated in splenocytes and the IFN-γ/IL-10 was elevated in sera of DKO-inoculated animals at later stages of infection indicating they have pro-inflammatory reactivity to parasite antigen." (PMID 37185599, 2023). "Thus, in several infectious diseases (viral, bacterial, fungal, parasitic), the effect of IL-10 varies by stage of infection and by tissue." (PMID 38019897, 2023). "Therefore, C. jejuni-infected microbiota-depleted IL-10−/− mice were orally treated with the compounds alone or all in combination from day 2 until day 6 post-infection." (PMID 37896170, 2023). "In addition, in infection-free mice, genetic overexpression of IL-10 in stromal cells indirectly stimulates T cells to produce IFN-γ, which acts on hematopoietic progenitors to induce myelopoiesis." (PMID 36719648, 2023). "It has the potential to influence our understanding of the immune interaction between IL-10 and parasitic and other infections and could lead to future strategies to targeted prevention and treatment of pathogens." (PMID 36370291, 2023). "Overall, infection by ΔPdh resulted in a 5-fold increase in the IL-10/TNFα ratio." (PMID 37384800, 2023). "Finally, inhibiting IL-10 signaling or co-administering arginine at the time of P. aeruginosa infection prolonged or restored survival in an otherwise 100% fatal burn and infection model." (PMID 37929965, 2023). "Direct LOAd732 infection in DCs resulted in a lower DC activation profile compared to LOAd703, but LOAd732-stimulated DCs showed a higher IL-12/IL-10 ratio, which may favor Th1 responses." (PMID 37501121, 2023). "However, IL-4 induces the polarization of Th0 to the Th2 subset, and the production of IL-4 and IL-10 inhibits the anti-infection process and leads to the dissemination of M. tuberculosis." (PMID 38140143, 2023). "However, the expression of IL-10 in L. pentosus treatments was comparable to that in the infection group." (PMID 37630849, 2023). "In this context, the roles of IL-10 in the host defense against infections have been reported." (PMID 36719648, 2023). "In summary, Sap2‐273L infected mice displayed higher fungal load overall, less C3a release all the time, more exhausted CD4+ T cells, Treg cells and M2 macrophage induced, as well as less pro‐inflammatory cytokines released, but more IL‐10 and IL‐9 production at day 12 post‐infection." (PMID 37211685, 2023). "However, significant differences were noticed in the levels of regulatory cytokines IL-10 and IL-4, wherein M.smeg::MtbEspR infection showed higher cytokine titers, clearly pointing to an inclination towards Th2 immune response." (PMID 37928551, 2023). "For instance, genetic variants in IL13, IL4, IL10, IFNG and STAT6 genes were associated not only with infection intensities and re-infection of S. mansoni after treatment, but also with S. haematobium infections and its infection intensities." (PMID 36889485, 2023). "High IL-10 production, occurring during the early phase of viral encephalitis, leads to decreased microglia activation, immune cells infiltration and proinflammatory factors release and an increased regulatory T cell rate in the site of infection." (PMID 37359549, 2023). "In consequence, the microbiota-depleted IL-10−/− mice are not only stably infected by the enteropathogen upon oral challenge, but also develop C. jejuni-induced acute enterocolitis with bloody diarrhea and wasting symptoms within a week post-infection (p.i.)." (PMID 37896170, 2023).
infection (continued). "Some studies have shown that the balanced secretion of anti-inflammatory and pro-inflammatory cytokines, such as IL-10 and IL-6, is characteristic of asymptomatic infections, whereas in symptomatic infections, there is a predominance of pro-inflammatory cytokines." (PMID 37896826, 2023). "Additionally, the compound appeared to perform immunomodulatory activity toward macrophages’ infection management due to the down expression of the pro-Leishmania cytokines IL-10 and IL-6." (PMID 37259353, 2023). "Although these cells are possible IL-10 producers, the importance of IL-10 in the BM during infection-induced EM remains unknown." (PMID 36719648, 2023). "Indeed, we found that compared to wild-type BCG infection, infection of mice with B∆tbcm led to reduced inflammation in lung tissue, possibly via an increased regulatory T-cell subset followed by enhanced IL-10 production." (PMID 38110948, 2023). "This dynamic study of F. gigantica-infected buffalo serum cytokines has revealed that, in the early stages of both primary and secondary infection, Th2/Treg dominated response was induced; this was manifested in increases of IL-4, IL-5, IL-10, IL-13, and TGF-β and reduction of IFN-γ and IL-17." (PMID 37152685, 2023). "Finally, we detected equivalent levels of IL-2, IFN-y, TNF-α, IL-12, IL-17, IL-22, IL-23, TGF-β, and IL-10 in the lungs of anti-Gr1-treated and control mice during the chronic phase of infection." (PMID 36776848, 2023). "Interestingly, the reduction of IL-10 secreting cells by IFNγ translated to bulk cultures, suggesting that during infection homeostasis is more easily steered into excessive inflammation, rather than insufficient response." (PMID 36911668, 2023). "TLR agonists are able to inhibit IL-10 responsiveness, and maybe in this way, promote the retention of AMs at the infection site and unleash their production of TNF-α." (PMID 37081878, 2023). "Interestingly, the NK cell-derived IL-10 appears to play dual roles in different types of infections." (PMID 36776839, 2023). "Interestingly, we observed a higher Interleukin-10 gene expression in the future HS pigs at two time points before infection." (PMID 36629432, 2023). "The deletion of Blimp-1 in T cells leads to a reduction of CD4+Foxp3+ T cells during the acute phase of infection and significantly decreased IL-10 production on day 12 post-infection, which could explain the observed increased inflammation." (PMID 37908369, 2023). "A single dose of the crude P. granatum peel extract HCEPg modulated the immune system by activating phagocytes and lymphocytes at the site of infection, controlling inflammatory responses by increasing IL-10 production and regulating H2O2 release by peritoneal cells." (PMID 37621924, 2023). "Therefore, results suggested a negative correlation between secretion of IL-10 and survival, so that animals that succumbed to infection displayed an increase of IL-10 serum values." (PMID 36680273, 2023). "At 24 h postinfection, the Δgroup5437 and Δgroup6178 infection groups exhibited significantly higher levels of IL-10 (an anti-inflammatory cytokine) than the WT group; however, these two groups simultaneously showed higher levels of induction of proinflammatory mediators (IL-1β and iNOS)." (PMID 37191575, 2023). "To test this, we compared WT and ΔPdh infection of IL-10+/+ and IL-10-/- C57BL/6 mice." (PMID 37384800, 2023). "Despite these limitations, the present study was able to show that symptomatic P. falciparum infection is associated with increased levels of the cytokines IL-10, IL-13, IL-6, IFN-γ and IL-12p70 while asymptomatic infection is marked by increased levels of IL-10, IL-13, IL-22 and IL-12p70." (PMID 36787308, 2023). "Stimulation of B cells or infection with B. microti resulted in the production of IL-10." (PMID 37492527, 2023).
infection (continued). "A possible reason for the low abundance of cDC1 could be due to IL-10, which is produced at an elevated level by various cells (e.g., DCs [our current findings], T cells, macrophages, etc.)during LD infection." (PMID 37202419, 2023). "IL-10 suppresses adaptive immune responses and impairs the control and clearance of pathogens in multiple infection models, suggesting that the upregulation of IL-10 levels might contribute to the failure in viral clearance." (PMID 36922500, 2023). "Additionally, dietary Se enhances immune responses and increases the production of immune-related molecules, such as interleukin-10 (IL-10) and immunoglobulin A (IgA), which are critical for immune regulation and defense against infection." (PMID 37760378, 2023). "Notably, we observed that IL-10 and IL-10-expressing macrophages were significantly increased in the uterine tissues of WT mice compared with TLR2/4-deficient mice, during infection with HylB-proficient GBS in vivo." (PMID 37747229, 2023). "IMs in the lungs, regulate T-cells and DCs by producing IL-10 during infection." (PMID 37965344, 2023). "Similarly, the anti-inflammatory IL-10 also presented that pattern at 0.5 h; however, at 1.5 h minutes of infection, IL-10 secretion was significantly higher in persister-infected macrophages than in infections with regular vegetative cells." (PMID 36920189, 2023). "The IL-10 expression, on the other hand, increased towards day 14 post infection." (PMID 37376505, 2023). "Moreover, serum IL-6 and IL-10 in the GN-BSI group sharply increased within 6 h post-infection, reaching peak levels around 6 h, and then gradually decreased to their original levels within 48 h." (PMID 37986183, 2023). "The expression of IL-6, and IL-10 was highly reduced in Xiap−/− DCs during infection with ST-OVA." (PMID 37347786, 2023). "However, similar to the present work, AMs from young horses had higher TNF-α gene expression and lower IL-10 expression than MDMs after infection with virulent Rhodococcus equi." (PMID 36920969, 2023). "Several clinical studies have described a huge increase in IL-10 early after few days from infection, after the concomitant increase of various other pro-inflammatory cytokines (such as TNF-α, IL-6, IL-1), as distinctive trait of the hyperinflammatory state developed upon SARS-CoV-2 infection." (PMID 37359549, 2023). "In addition, lycopene can improve broiler fertility by enhancing sperm performance and reducing inflammation by modulating the levels of interleukin 1, 2, and 10 (IL-1, IL-2, and IL-10) in cases of infection." (PMID 37426426, 2023). "Our data also suggest that MFD reduces inflammation and necrotic damage in the lungs during the chronic stage of infection compared to RD, and that these changes may involve adipocyte physiology and adipose tissue-derived anti-inflammatory IL-10." (PMID 36676177, 2023). "Moreover, neonates born to mothers with recent or ongoing infection express higher plasma levels of IL-10 and CXCL8 than their paired mothers." (PMID 37242334, 2023). "Additionally, as a major suppressor of the immune response and a key player in human disease, the regulation of IL-10 has great potential for the treatment of inflammatory and neurodegenerative diseases, infection, and even cancer." (PMID 36541788, 2023). "The increase in expression of IL-10 during the infection process might be playing a role to maintain an appropriate balance of inflammatory response." (PMID 36792637, 2023). "Consistent with this, the loss of IL-10 in IL-10-/- mice does not alter growth/damage balance for infection by the WT strain, but does for infection by ΔPdh." (PMID 37384800, 2023). "Adaptation of the test to measure IL‐10 could be used as a biomarker of subsequent infection to guide clinical treatment decisions." (PMID 37125245, 2023). "Infection with ∆eseN induced IL-10 production at 3 h PI compared to infection with WT at 3 h PI." (PMID 37796003, 2023).
infection (continued). "We also found two cytokines down-regulated, a pro-inflammatory il15 gene, which promotes Th1 responses and T-cell maturation, and il10, an anti-inflammatory gene that is expressed under infection with stimulatory and inhibitory activities on several immune cells." (PMID 37422657, 2023). "In this study, HLA-A11/DR1 mice were subjected to IL-10 intervention at 48 h post-infection, resulting in an enhanced clearance of bacteria from the bloodstream and various organs (including the liver, kidney, and spleen) at 72 h post-infection." (PMID 38035330, 2023). "It would be interesting to determine whether granulocyte depletion with anti-Ly6G at later stages of craniotomy infection would promote bacterial clearance given the known immunosuppressive role of IL-10 at this interval." (PMID 37179295, 2023). "DHAV infection could lead to the different expression of various cytokines in young ducklings; for example, the transcription of IL-1β, IL-2, IL-4, IL-6, IL-8, and IL-10 was highly stimulated after infection." (PMID 37391858, 2023). "To test this hypothesis, we performed whole-cell patch-clamp recordings in acute brain slices prepared from IL-10−/− mice with hyperinflammatory eCM on day 7 post-infection (p.i.)." (PMID 38115011, 2023). "After infection, animals generate IL-4, IL-5, and IL-10, resulting in a Th2 response." (PMID 37110723, 2023). "Finally, in vivo expansion of endogenous Leishmania-specific Tregs led to reactivation of disease at the primary infection site which correlated with reduced effector Th1 responses in an IL-10 dependent manner." (PMID 38114497, 2023). "Similarly, both Foxp3+ and Foxp3− CD4+ T cells produced IL-10 upon infection in IL-4α−/− BALB/c mice." (PMID 38114497, 2023). "However, an increase in anti-inflammatory mediators has also been reported, for example, IL-10, which can negatively interfere in the fight against the parasite and enable its multiplication, thus inducing the worsening of the infection." (PMID 37235324, 2023). "Additionally, Bregs have been shown to be recruited to the site of infection to suppress damaging inflammation in the lung tissues through the production of IL‐10 or IL-358." (PMID 37833265, 2023). "IL-10 is a complex pleiotropic cytokine that has been highly studied in several autoimmune and infectious diseases and possess complex actions that vary by stage of infection and by tissue." (PMID 38019897, 2023). "Prior studies of cytokines in blood have found that IL-6, IL-10, and TNF-α increase in burn compared to healthy pediatric patients, that elevated circulating TNF-α is associated with death, and that decreased circulating TNF-α/IL-10 ratio is correlated with an increased chance of infection." (PMID 36790939, 2023). "Thus, it is possible that the decrease in circulating NK cell frequency is the result of IL-10–mediated activation and recruitment to the infection site." (PMID 37490342, 2023). "However, there is a paucity of literature addressing the localized production of IL-10 by specific cell types in response to bacterial infections and the consequent impact on the progression of infection." (PMID 37747229, 2023). "However, blocking IL-10 signaling reversed the outcome in Bhlhe40−/− mice, suggesting that excess IL-10 production limits their ability to control the infection properly." (PMID 37843306, 2023). "In the gill, IL-10 stabilized following upregulation at 7 dpd and may therefore indicate recovery from infection." (PMID 37649642, 2023). "Importantly, the high IFN-γ levels were sustained during infection while increasing production of IL-4 and IL-10 was also detected." (PMID 37631952, 2023). "Therefore, our initial exploration was also more focused on identifying IL-10-producing Breg cells induced by Cm infection." (PMID 37759658, 2023).